MTOR (mechanistic target of rapamycin kinase)
Diseases named in the same sentence as MTOR in open-access papers (continued):
Sharing a sentence is not in itself a finding about the gene and the disease.
cutaneous squamous cell carcinoma (13 papers, 2012 to 2026). "This study provides a systematic analysis of the association between the PI3K/AKT/mTOR signaling pathway and cutaneous squamous cell carcinoma (cSCC)." (PMID 41438693, 2026). "•Dentifies a novel diagnostic model for cutaneous squamous cell carcinoma (cSCC) using 11 PI3K/AKT/mTOR pathway hub genes." (PMID 41438693, 2026). "The aberrant activation of the PI3K/AKT/mTOR pathway in cutaneous squamous cell carcinoma (cSCC) has been extensively investigated." (PMID 41438693, 2026). "In epidermal tumors such as cutaneous squamous cell carcinoma (cSCC) and precancerous actinic keratoses (AKs), the mTOR pathway exhibits elevated phosphorylation levels of mTOR, AKT, and their downstream effectors in comparison to normal skin." (PMID 39063983, 2024). "Previous research demonstrated benefits of late conversion to mTOR inhibitors against cutaneous squamous cell carcinomas (cSCC) in kidney transplant recipients (KTR), despite of poor tolerability." (PMID 37565728, 2023). "The aim of this study is to explore the role of mammalian target of rapamycin (mTOR) in cutaneous squamous cell carcinoma (CSCC), Bowen’s disease (BD), and actinic keratosis (AK) with squamous cell differentiation abnormality and its relationship with the degree of tumor proliferation." (PMID 34874800, 2021). "In this study, we showed for the first time that the promising anticarcinogenic flavonoid Luteolin (LUT) decreased AKT/mTOR signaling and in parallel induced caspase-dependent cell death in both primary and metastatic cutaneous squamous cell carcinoma (SCC) cells." (PMID 23110223, 2012). "Similarly, both pS6 and pAKT are significantly overexpressed in feline cutaneous squamous cell carcinomas (CSCC), suggesting the mTOR pathway plays a critical role in the pathogenesis of feline CSCC and may represent a potential therapeutic target." (PMID 40711277, 2025).
Fanconi anemia (13 papers, 2019 to 2025). Fanconi anemia (FA) is a hereditary DNA repair disorder characterized by progressive pancytopenia with bone marrow failure, variable congenital malformations and predisposition to develop hematological or solid tumors. "LOF germline variants also were identified in other Fanconi anemia genes and in MAPK and PI3K/AKT/mTOR pathway genes." (PMID 37460928, 2023). "Loss-of-function germline variants also were identified in other Fanconi anemia genes and in MAPK and PI3K/AKT/mTOR pathway genes." (PMID 36865331, 2023). "KEGG analysis showed that the “Fanconi anemia pathway” (p = 0.003) was the most commonly enriched of the 173 signaling pathways identified, followed by the “mTOR signaling pathway” (p = 0.008), “Influenza A” (p = 0.04) and “Growth hormone synthesis, secretion and action” (p = 0.046)." (PMID 33499090, 2021). "Hyperactive mTOR signaling is known to contribute to CDDP resistance, for example, by upregulating FancD2, an essential protein in the Fanconi anemia DNA repair pathway, which promotes repair of lethal CDDP-induced DNA interstrand crosslinks." (PMID 32943635, 2020). "While mTOR signaling pathway, WNT signaling pathway and PI3K-Akt signaling pathway; collecting duct acid secretion, fanconi anemia pathway, N-Glycan biosynthesis and adherens junction were the top enriched pathways for D15 vs D90, D15 vs D250 and D90 vs D250 comparison groups in Kashmiri cattle." (PMID 35246027, 2022).
graft versus host disease (13 papers, 2010 to 2025). An immune system disorder that occurs after allogeneic hematopoietic stem cell transplant and is a reaction of donor immune cells against host tissues. "Sirolimus, also named as rapamycin, is a mTOR inhibitor which has been successfully used for the prevention of graft-versus-host disease." (PMID 40606852, 2025). "Reduction in Tconv glycolytic activity via mTOR inhibition results in a more Treg-like metabolic profile, and this mTOR inhibition-mediated Tconv functional shift also prevented the induction of graft-versus-host disease (GvHD)." (PMID 38993904, 2023). "One current approach to prevent graft vs host disease (GvHD) is to use immunosuppressants to down-regulate normal immune functions, including using anti-proliferative agents, steroids, mTOR inhibitors, and Calcineurin inhibitors." (PMID 33912156, 2021). "Clinic studies have revealed similar importance for mTOR in skin wound healing, as evidenced by the development of skin ulcerations and chronic wounds following treatment with mTOR inhibitor, everolimus, to prevent graft rejection in graft-versus-host-disease." (PMID 35938153, 2022). "A recent study from our laboratory demonstrated that ex-vivo treatment of donor cells with WA could ameliorate the onset of Graft versus Host Disease (GvHD) in mouse model of allogeneic bone marrow transplantation by modulating Akt-mTOR signaling pathway." (PMID 36518386, 2022). "Patients chosen for inclusion received graft-versus-host disease (GVHD) prophylaxis with the mTOR inhibitor sirolimus (12-mg loading doses on days 1-3 followed by 4 mg daily) or standard GVHD prophylaxis (cyclosporine or tacrolimus alone or in combination with methotrexate)." (PMID 21092307, 2010). "The mTOR enzyme induces metabolic reprogramming of alloantigen activated T-cells after allogeneic hematopoietic stem cell transplantation, which utilizes the glycolytic pathway to sustain alloreactive T cells mediated graft versus host disease (GvHD)." (PMID 35844500, 2022). "Combined OX40L and mTOR blockade in nonhuman primate graft-versus-host disease (GVHD) model prolonged survival by controlling effector T cell activation while preserving Treg reconstitution." (PMID 34234777, 2021).
hepatoblastoma (13 papers, 2016 to 2026). Hepatoblastoma (HB) is a malignant hepatic tumor and is the most common pediatric liver cancer. "A previous study also depicted the role of mTOR in the development of hepatoblastoma in association with YAP-1-β-catenin signaling cascade." (PMID 31511432, 2019). "The miR-193a-5p/DPEP1 axis regulates hepatoblastoma progression via the PI3K/Akt/mTOR signaling pathway." (PMID 40161373, 2025). "CRNDE up-regulation contributes to tumor growth and hypervascularity of hepatoblastoma via mTOR signaling activation." (PMID 28178668, 2017). "Abnormal EGFR signaling together with dysregulated Wnt, JAK/STAT and mTOR signaling pathway genes has been observed in transcriptome sequencing of the HepG2 hepatoblastoma cells." (PMID 27910913, 2016). "mTOR is activated downstream of YAP/TAZ in a YAP/β-catenin hepatoblastoma mouse model." (PMID 37414763, 2023). "mTOR signaling pathway is activated in hepatoblastoma cells and hepatoblastoma tissues." (PMID 28178668, 2017). "We reveal a direct interaction between CRNDE and mTOR in hepatoblastoma." (PMID 28178668, 2017). "In Yap1-β-catenin mice model, treatment with rapamycin (mammalian target of rapamycin (mTOR) inhibitor) was shown to attenuate the tumor growth over a period of time along with inhibition of mTORC1 suggesting that mTCOR1 is a potential target in YAP-1-β-catenin signaling cascade in hepatoblastoma." (PMID 31511432, 2019). "We then determined whether mTOR signaling is activated in hepatoblastoma cells." (PMID 28178668, 2017). "Moreover, inhibition of mTOR signaling could inhibit CRNDE overexpression-induced up-regulation of hepatoblastoma cell viability and abnormal angiogenic effect." (PMID 28178668, 2017). "The interaction between β-catenin and YAP-1 protein may activate mTOR pathway to increase the expression of amino acid transporter, i.e. SLC38A1, which may be critical in the development of hepatoblastoma." (PMID 31511432, 2019). "Moreover, this signaling pathway interconnects other targets including ERK1/2, glypican, mTOR and YAP in the development and progression of hepatoblastoma." (PMID 31511432, 2019). "Moreover, phosphorylated mTOR and P70S6K level was significantly higher in hepatoblastoma tissues compared with the matched normal tissues." (PMID 28178668, 2017). "There has been an exploration of new targets in the management of hepatoblastoma including signal transducer and activator of transcription signaling 3 (STAT3); NOTCH receptors and their ligands; PI3K/Akt, ERK and p38 signaling pathways; GPC3; PIM Kinases; ROCK1; mTOR and YAP." (PMID 31511432, 2019). "Phosphorylated mTOR and P70S6K (a serine/threonine kinase that is directly downstream of mTOR) expression was much higher in hepatoblastoma cells (HuH-6) than that in nonmalignant QSG-7701 and L02 cells, indicating that mTOR signaling was activated in hepatoblastoma cells." (PMID 28178668, 2017).
HIV-1 infection (13 papers, 2013 to 2025). The type species of lentivirus and the etiologic agent of acquired immunodeficiency syndrome (AIDS). "Consistent with this, we have also previously observed microtubule acetylation during HIV-1 infection and observed that preventing microtubule acetylation through the use of an mTOR inhibitor, which depletes cellular acetyl-CoA pools, inhibits HIV-1 infection." (PMID 39804091, 2025). "Early in HIV-1 infection, Tat enhances autophagy in host cells through the inhibition of the mechanistic target of rapamycin [mTOR], a master regulator that normally suppresses autophagy." (PMID 40072080, 2025). "Notably, previous studies examining the role of microtubule acetylation in HIV-1 infection have shown reduced infection under conditions involving viral mutations and mTOR inhibition, though these interventions may have broader effects on viral infectivity and cell viability." (PMID 39804091, 2025). "HIV-1 infection has been shown to interfere with mTOR signaling, which usually results in diminished mTOR expression levels in immune cells, particularly in CD4+ T cells." (PMID 36992700, 2023). "mTOR’s upstream and downstream signaling molecules are altered by HIV-1 infection to regulate the viral life cycle and latency, which will be a central theme in this review." (PMID 36467738, 2022). "HIV-1 infection and mTOR activation increase levels of the one-carbon metabolism substrate, serine, through upregulating the amino acid transporter ASCT2." (PMID 36467738, 2022). "HIV-1 infection increases acetyl-CoA abundance through both increased glucose and glutamine transport mediated via Akt and mTOR signaling." (PMID 36467738, 2022). "This further shows the importance of mTOR activation in HIV-1 infection, as PPP activity is required for nucleotide synthesis and generation of lipids required for virion production." (PMID 36467738, 2022). "Other examples include how the mechanistic target of rapamycin (mTOR) mediates MT stabilization to facilitate early HIV-1 infection in T cells." (PMID 34229718, 2021). "Further, mTOR inhibition has been found to activate autophagy during HIV-1 infection resulting in induced clearance of HIV-1 transcription factors (i.e., Tat)." (PMID 32823598, 2020). "HIV-1 infection can inhibit autophagy and activate mTOR, which is known to play an important role in gp120-induced apoptosis." (PMID 23773913, 2013). "Notably, the top neuronal upstream regulator genes activated by HIV-1 infection in the AD context included APP, presenilin-1, microtubule-associated protein tau (MAPT), and mammalian target of rapamycin (mTOR)." (PMID 40313365, 2025). "mTOR inhibitors perturb HIV-1 infection by inhibiting various steps of the HIV-1 life cycle." (PMID 33504604, 2021). "This adds mechanistic understanding, confirms earlier reports that catalytic inhibitors of mTOR hold promise for improving HIV-1 chemotherapy and prevention and suggests continued investigation of mTOR’s role in establishment as well as reactivation of HIV-1 infection." (PMID 28953320, 2017). "Thus, the mTOR pathway plays a role in efficient HIV-1 infection." (PMID 33504604, 2021). "Moreover, E. natalensis phytochemicals were significantly enriched in the HIV-1 infection pathway (hsa05170), with overlapping genes converging on PI3K–Akt–MTOR signaling, NFκβ activation, MAPK cascades, calcium signaling, Toll-like receptor signaling, TNF signaling, and apoptotic pathways." (PMID 41011481, 2025).
human papillomavirus infection (13 papers, 2022 to 2025). "The top five enriched pathways associated with upregulated miRNAs were human papillomavirus infection, focal adhesion, mTOR signaling pathway, axon guidance, and Wnt signaling pathway." (PMID 36531465, 2022). "Results from KEGG analysis demonstrated notable correlations between upregulated genes and multiple pathways, such as human papillomavirus infection, mTOR signaling, ECM-receptor interaction, and Wnt signaling." (PMID 41040951, 2025). "Top 5 of KEGG pathway enrichment analysis was “PI3K-Akt signaling pathway”, “MAPK signaling pathway”, “Human papillomavirus infection”, “mTOR signaling pathway”, “Insulin signaling pathway”." (PMID 36366842, 2023). "In hUC-MSC-Exos, the 61 unique miRNAs were found to participate in the regulation of PI3K-AKT signaling, human papillomavirus infection, cGMP-PKG signaling, cellular senescence, Ras signaling, mTOR signaling, JAK-STAT signaling, NF-κB signaling, etc." (PMID 36064647, 2022).
inflammatory skin disease (13 papers, 2016 to 2025). Inflammatory skin disorders covers a broad category that includes many conditions ranging in severity, from mild itching to grave medical health complications These disorders are common in people of all ages and races. "Our findings in skin development corroborate recent reports of a dysregulated mTOR pathway as a pathogenic factor in hyperplastic or inflammatory skin diseases, and hence their therapy with inhibitors of mTOR signalling." (PMID 27807348, 2016). "The PI3K/AKT axis plays a significant role in inflammatory skin diseases, with a particular focus on its downstream target, the mechanistic target of rapamycin (mTOR), which is central to some of the most common inflammatory skin conditions." (PMID 39861704, 2025). "Several studies have revealed that certain natural products and synthetic compounds can obstruct the expression/activity of PI3K/Akt/mTOR, underscoring their potential in managing common and persistent skin inflammatory disorders." (PMID 37371141, 2023). "To date, mTOR inhibitors have been extensively studied for the treatment of inflammatory skin diseases as well as cancers." (PMID 37371141, 2023). "Some publications have discussed the effects of natural products and/or synthetic scaffolds on the PI3K-Akt-mTOR pathway components with regard to hyperproliferative or specific inflammatory skin disorders or skin cancer type." (PMID 37371141, 2023). "Taken together, these findings strongly demonstrate the altered epidermal mTOR signaling status under skin inflammatory disease conditions and suggest that inhibition of mTOR signaling activity as a promising treatment for inflammatory skin disease in general." (PMID 35938153, 2022). "Studies have shown that UVB irradiation can activate the up-regulation of the PI3K/AKT/mTOR signalling pathway in keratinocytes, in which the high activation of AKT/mTOR will increase the content of inflammatory factors in cells, leading to inflammatory skin diseases." (PMID 36771204, 2023). "To determine whether mTOR signaling plays a role in the development of rosacea, we detected the expression of pS6, the phosphorylated form of the mTORC1 downstream molecule S6, in skin samples from rosacea and HS, or patients with other facial inflammatory skin diseases of similar symptoms." (PMID 33734592, 2021).
leiomyoma (13 papers, 2012 to 2026). A well-circumscribed benign smooth muscle neoplasm characterized by the presence of spindle cells with cigar-shaped nuclei, interlacing fascicles, and a whorled pattern. "Studies have shown that mTOR inhibitors are a potential effective treatment for UL and other special types of leiomyomas, including PBML." (PMID 37189093, 2023). "The PI3K/Akt pathway participates in the regulation of mammalian target of rapamycin (mTOR), and modulates cancer cell survival, proliferation, and apoptosis, therefore playing an important role in cancer progression and in leiomyoma." (PMID 34578952, 2021). "PrRP activated the PI3K B/Akt-mammalian target of rapamycin (PI3K-Akt-mTOR) pathways and cell proliferation in primary leiomyoma cells, where GPR10 is aberrantly expressed." (PMID 31653061, 2019). "The leiomyoma was treated conservatively, with the patient switched from cyclosporine and azathioprine to the mTOR inhibitor everolimus." (PMID 27195169, 2016). "Eker rats develop spontaneous renal tumors and leiomyoma, which may be due to tuberous sclerosis 2 (TSC2) mutation resulting in the activation of the mammalian target of the rapamycin (mTOR) pathway." (PMID 35405980, 2022). "Importantly, in human leiomyomas, most of these signaling pathways, such as upregulation of mTOR, TGFB1 and CTNNB1 pathway, deregulation of IGF-1 signaling in human uterine leiomyoma and inflammatory process involving TNF signaling have been reported." (PMID 33244099, 2020). "In fact, the PI3K/Akt-mTOR pathway has been identified as one of the most upregulated signaling pathways in leiomyomas, based on evidence from protein and transcriptional profiling of human leiomyomas, as well as in an Eker rat animal model." (PMID 31159158, 2019). "The upregulation of mTOR signaling is also observed in human smooth muscle tumors of the uterus known as leiomyomas and similar tumors were developed in Eker rat with defective TSC2 signaling confirming that the mTORC1 pathway plays an important role in the pathogenesis of these tumors." (PMID 22916036, 2012). "Metformin inhibits the growth of the leiomyoma, and this effect is mediated by the activation of the AMPK and by the subsequent inhibition of the mammalian target of rapamycin (mTOR) pathway." (PMID 27070597, 2016).